BCOR (BCL6 corepressor)
Diseases named in the same sentence as BCOR in open-access papers (continued):
Sharing a sentence is not in itself a finding about the gene and the disease.
tumor (119 papers, 2014 to 2026). "Accordingly, a loss of function mutation in the BCOR gene interrupts tumor suppression functioning and thereby leads to tumorigenesis." (PMID 40724977, 2025). "Based on the tumor-suppressor role of BCOR, we investigated the impact of Bcor loss in the context of CLL evolution through the generation of an in vivo pre-clinical model." (PMID 40113912, 2025). "Upon further refinement—requiring validation by three or more sources—six unique genes were identified in the FPoriginal-only list, including BCOR, a known tumor suppressor associated with oncogenic fusions." (PMID 40857351, 2025). "Patient 63 acquired subclonal mutations in FUBP1:p.I271Rfs*3 and BCOR:p.D1355N when tumor recurrence was observed." (PMID 37533228, 2023). "The pattern of BCOR aberrations, including nonsense mutations, frame-shift mutations, mutations leading to splicing errors, and gene loss suggested a tumor-suppressor role for BCOR." (PMID 35054466, 2022). "An intriguing correlation was found for BCOR protein expression with gene fusion variants, size, and tumor location." (PMID 34680383, 2021). "BCOR/BCORL1 mutations are found in an array of cancers, and inactivating BCOR mutations have been identified in various hematological, epithelial and central nervous system (CNS) neoplasms." (PMID 34617019, 2021). "Our study revealed that BCOR immunoreactivity is frequent in SFTs and that it is tightly associated with fusion variant and tumor size and location." (PMID 34680383, 2021). "The first pattern was obtaining new gene mutations (transformation-related mutations) based on BCOR mutation, involving tumor signaling molecules, transcription factors or tumor suppressor genes." (PMID 34461985, 2021). "Whole-genome sequencing of 4 and whole-exome sequencing of 71 tumor samples showed that only BCOR and CREBBP were mutated in 10% and 4% of the cases, respectively." (PMID 28099942, 2017). "On the other hand, the BCOR gene is located on the X-chromosome, available as only one allele, so that the fusion in the index case would potentially lead to a complete loss of putative tumor-suppressor activity mediated by the PUFD." (PMID 38637838, 2024). "Given their morphological and epigenetic similarities, circumscribed CNS tumors with EP300/CREBBP::BCOR(L1) fusions and CNS tumors with BCOR ITD may represent variants of the same tumor type." (PMID 38216991, 2024). "Abnormal regulation of DNA replication coupled processes could be linked to tumorigenesis, as shown by the tumor suppressive role of BCOR and the paradoxical roles of KDM2B in prevention or promotion of malignant transformation of HSPCs31–34,56,57." (PMID 36443290, 2022). "Mutations of BCOR were identified in 5 out of 21 tumours, an incidence of 24%." (PMID 33670346, 2021). "Our investigation on new molecular features awaits further confirmation, but it may offer new markers that could be useful as surrogates for tumor characterization (BCOR expression) and relevant for patient risk stratification (NTRK expression)." (PMID 34680383, 2021). "None of the patients showed SMARCA4 loss; one patient was positive for BCOR (80% of tumor cells)." (PMID 32972432, 2020). "EBV-positive tumours, including solid tumours, have been noted to harbour BCOR mutations suggesting that BCOR mutations may be an important aspect of EBV-related pathogenesis." (PMID 30876435, 2019).
tumor (continued). "We have shown experimentally, for the first time, that Bcor can act as a tumour suppressor gene and the distinct gene-expression signature of Bcor-mutant lymphomas suggests that BCOR loss-of-function may subvert TGFβ signalling to drive lymphoma development." (PMID 28262675, 2017). "Indeed, NGS analysis revealed that 40% of analyzed tumors, in addition to BCOR exon 15 internal tandem duplication, harbor other likely pathogenic genetic alterations, what may have an impact on tumor behavior." (PMID 32650833, 2020). "Limited information exists for this exceptionally rare tumor that is characterized by the presence of a BCOR/BCOR(L1) fusion, copy number variations within chromosomes Xp11.4 and 22q12.31, or truncating small nucleotide variants." (PMID 40724977, 2025). "Central nervous system (CNS) tumor with BCL6 corepressor gene BCOR/BCORL1 fusion is an extremely rare tumor entity, with fewer than 40 cases reported." (PMID 40724977, 2025). "The 2021 WHO classification of CNS tumors defined a new CNS-PNET tumor entity: CNS tumor with BCL6 corepressor gene (BCOR) internal tandem duplication (ITD)." (PMID 40724977, 2025). "A single tumor (Case 1) was also tested for BCOR gene rearrangement by fluorescence in situ hybridization, which was positive, with 75% of the tumor cell nuclei displaying red-green “split” signals." (PMID 40705064, 2025). "In this context, BCOR immunoexpression in ≥50% of tumor cells can serve as a useful screening tool for selecting cases for molecular testing to confirm HG-ESS." (PMID 41463261, 2025). "BCOR-ITD is a newly identified tumor among CNS-PNETs, wherein a match to this methylation class on DNA methylation profiling is an essential criterion for unresolved cases." (PMID 40724977, 2025). "On next-generation sequencing (NGS), six tumors revealed ZC3H7B::BCOR fusion, including ZC3H7Bex10::BCORex6 (n = 4), ZC3H7Bex12::BCORex7 (n = 1), ZC3H7Bex12::BCORex6 (n = 1), and one tumor revealed ZC3H7Aex10::BCORex6 fusion." (PMID 40705064, 2025). "On the protein level all analyzed tumor samples of this study showed nuclear staining of BCOR, but internal tandem duplications in exon 15 of the BCOR gene or BCOR gene fusions were absent." (PMID 41291966, 2025). "The molecular hallmark of this tumor, BCOR ITD, is shared by multiple extra-CNS neoplasms leading to a debate regarding the neuroepithelial or mesenchymal nature of this tumor." (PMID 37658995, 2024). "CNS tumor with BCOR/BCOR(L1)-fusion seems to be an independently existing tumor type with archetypical histological and molecular features, however, consistent diagnostic criteria are still missing." (PMID 38637838, 2024). "Instead, the tumor showed CREBBP::BCORL1 fusion and pathogenic mutations in BCOR and CREBBP, along with a DNA methylation profile matching the “CNS tumor with EP300:BCOR(L1) fusion” methylation class." (PMID 38216991, 2024). "BCOR is a highly sensitive marker in BCOR gene-rearranged tumors but is also often observed in SSs (around half the neoplasms)." (PMID 39062853, 2024). "In this study, we introduce a BCOR::CREBBP fusion in an adult patient with a right temporomediobasal tumor and methylation class “CNS tumor with BCOR/BCOR(L1)-fusion”." (PMID 38637838, 2024). "Whole-exome sequencing (WES) and whole-transcriptome sequencing (WTS) were performed on six localized and three metastatic BCOR-ITD-positive CCSKs, confirming that this tumor carries a low mutational burden." (PMID 36835166, 2023).
tumor (continued). "The Central Nervous System (CNS) tumor with BCOR internal tandem duplication (ITD) has recently been added as a novel embryonal histomolecular tumor type to the 2021 World Health Organization (WHO) Classification of CNS Tumors." (PMID 36782314, 2023). "Tumor cells were diffusely positive for Synaptophysin, CD56, INI1 and SMARCA4 associated with negativity for GFAP, OLIG-2, EMA, BCOR, LIN28A and MIC-2." (PMID 36934287, 2023). "These BCOR‐ITD tumors are reported to be aggressive tumor entities with an ITD in the last exon of the BCOR gene." (PMID 37212486, 2023). "Next-generation sequencing (NGS testing) of the tumor tissue specimen showed internal tandem duplication of BCOR gene, thus confirming the diagnosis." (PMID 38170001, 2023). "Tumor cells were diffusely positive for Synaptophysin, CD56, INI1, SMARCA4 and ATRX associated with negativity for GFAP, OLIG-2, EMA, BCOR, LIN28A, EZHIP, MIC-2, Cytokeratin’s, SMA, Desmin and Myogenin." (PMID 36934287, 2023). "Our cohort of patients harboring the BCOR rearrangement frequently had localized tumor, located in limbs and significantly younger at diagnosis than patients with “CIC fused” STS, confirming observations including locations in bone." (PMID 37212486, 2023). "For all CCSKs, the primary tumor sample was analyzed, and the presence of BCOR-ITD was confirmed by PCR and Sanger sequencing." (PMID 36835166, 2023). "CNS tumor with BCOR internal tandem duplication is a novel tumor type that will require further characterization and its origin." (PMID 35969220, 2022). "Only the BCOR‐ITD was included in clone 1, whereas three clade mutations (FLT1, JAK2, and MYH7) were additionally detected in relapsed tumor samples (clones 2, 3)." (PMID 34967151, 2022). "The tumor cone precursors were also characterized by the expression of DEK and BCOR, despite suggested loss of copy of number." (PMID 34003213, 2021). "The identification of the same BCOR genetic aberrations in so many different tumor types suggests a central pathogenetic role of this gene." (PMID 33099834, 2021). "We identified nonsynonymous SNVs in tumor tissues, such as SMARCA4 (in 192D0360T and 192D0641T), BCOR and LRP1B in 192D0641T, as well as frameshift mutations of KMT2D in 192D0695T and truncating mutations of PTCH1 in 192D0583T." (PMID 33707557, 2021). "We also checked the expression of selected genes among genes upregulated by BCOR K607E mutant in fresh-frozen tumor patient samples by qRT-PCR." (PMID 33468080, 2021). "The third tumor with inconclusive result revealed only focal BCOR immunopositivity of neoplastic cell nuclei." (PMID 32650833, 2020). "Three supratentorial tumors harboured BCOR exon 15 tandem duplication and in one tumor the result was inconclusive." (PMID 32650833, 2020). "In contrast, loss-of-function mutations in PRC genes, such as EZH2, EED, SUZ12, BCOR, and BCORL1, have been found in various hematological malignancies, suggesting their tumor suppressor functions." (PMID 33374737, 2020). "DNA was extracted from the FFPE tumor material and PCR using flanking primers, and subsequent Sanger sequencing revealed a large duplication within exon 15 of the BCOR gene." (PMID 30526817, 2019). "The mutations in these diseases almost always result in a premature stop codon and nonsense-mediated decay or protein truncation, strongly suggestive of a tumour suppressor role for BCOR in these contexts." (PMID 30902969, 2019).
tumor (continued). "These genes included those that have been reported to be associated with the biological behaviour of tumour cells (NTRK2, MAPK8, BCOR, and PIK3R1 genes)." (PMID 31034520, 2019). "The majority of tumor cells showed a strong nuclear BCOR immunoreactivity (C-10, 1 : 200, Santa Cruz Biotechnology, Dallas, TX, USA)." (PMID 30526817, 2019). "It was proposed that TGFβ drives Myc-induced senescence in a Suv39h1-dependent manner raising the intriguing possibility that BCOR also regulates this unique tumour suppressive mechanism." (PMID 28262675, 2017). "Endothelial activation by tumor cell supernatant resulted in peak levels of Bcl-6 and BCoR transcripts after 1–2 h and downregulation by 4 h." (PMID 27880939, 2017). "Apart from the three genes (RB1, BCOR, CREBBP) that showed somatic mutations in at least 2 different tumors, there were 199 other genes that were mutated in a single tumor only." (PMID 27126562, 2016). "The presence of the ITD was confirmed on tumor DNA and cDNA, and resulted in overexpression of BCOR." (PMID 26516930, 2015). "This structural variation may be relevant to RT oncogenic processes, potentially reducing the tumor suppressor function of BCOR." (PMID 40113912, 2025). "At genomic level, whole-genome sequencing and whole-exome sequencing did not identify mutations in the BCOR gene within the bulk tumor populations of RT samples." (PMID 40113912, 2025). "Collectively, the histomorphologic examination of our patient’s tumor corroborates other reported cases of CNS tumors with BCOR/BCOR(L1) fusion, which exhibit diverse histologic findings including oligodendroglial-like chicken-wire vasculature and/or ependymomal-like perivascular pseudorosettes." (PMID 40724977, 2025). "BCOR deletions hinder PRC1.1 tumor suppressor functioning and incomplete PRC1.1 dysfunction may be sufficiently adequate to promote tumorigenesis." (PMID 40724977, 2025). "However, the tumor expresses p16, BCOR, Cyclin D1, CD10, estrogen receptor [ER] and progesterone [PR]." (PMID 39877469, 2025). "Further BCOR variants were found in a PB-miRNA2 case with a homozygous DROSHA deletion (BCOR S17R; VAF = 100%, uncertain significance of pathogenity) and in a PB-miRNA1A tumor with a heterozygous DROSHA mutation (BCOR P120 frameshift deletion; VAF = 18%)." (PMID 41291966, 2025). "PUFD is an essential domain for tumor suppressor function of BCOR." (PMID 38637838, 2024). "However, other rare oncogenic fusions such as MN1, PATZ1, BCOR and CIC do appear to be diagnostic for specific tumor types." (PMID 39409964, 2024). "This study confirmed that BCOR-ITD-positive CCSKs are a cytogenetically stable tumor with few genomic alterations and without a specific mutation profile shared by metastatic cases." (PMID 36835166, 2023). "Despite that, DNA-methylation profiling could accurately classify many of the difficult-to-diagnose cases including all CNS NB-FOXR2-activated tumours, all ETMRs and all CNS tumours with BCOR ITD." (PMID 36895035, 2023). "Recently, the tumor suppressor function of BCOR has been confirmed in vivo in a Myc-driven lymphomagenesis model as well as in transgenic mice expressing a truncated form of BCOR (partial internal deletion) that cannot bind to BCL6." (PMID 33468080, 2021). "High BCOR IHC expression correlated with tumor size and location." (PMID 34680383, 2021). "Hence, we propose that BCOR plays the role of a tumor suppressor in the pathogenesis of T lymphocyte malignancies." (PMID 33468080, 2021). "Mutations in genes such as AKT1, BCOR, and PIK3R1 were also observed and these genes may also contribute to tumor development." (PMID 31101826, 2019).
tumor (continued). "Thus, while the roles of some PRC1 components in cancer seems mostly related to their requirement for stem cell survival, BCOR appears to be a bona fide tumor suppressor." (PMID 31123059, 2019). "Furthermore, it is essential to note that endothelial Bcl-6/BCoR were found to be induced by tumor-derived stimuli in our initial experiments." (PMID 27880939, 2017). "However, subsequent transcript analysis by quantitative real-time PCR demonstrated a rapid, 5- to 17-fold induction of both Bcl-6 and BCoR mRNA in ECs within 1 h of stimulation with tumor-derived signals." (PMID 27880939, 2017). "We found BCoR mRNA to be prominently induced in endothelial cells in response to tumor signals." (PMID 27880939, 2017). "Actually, our recent study has reported that BCOR, a main component of PRC1.1 is frequently mutated in human MBSHHs; its deletion increases Igf2 transcriptional activation via histone H2A modification, causing enhanced tumor progression in SHH-driven murine tumors." (PMID 35573667, 2022). "Although neither demonstrated LOH across the BCOR locus, it is possible that the alternative parental allele in these two tumours may be affected by X-inactivation." (PMID 33670346, 2021). "Second, the novel ability to characterize tumor-specific somatic mutations in vivo, at diagnosis, creates opportunity for larger, prospective studies investigating the prognostic value of specific somatic RB1 alterations or other pathogenic mutations, such as BCOR or CREBBP." (PMID 33805776, 2021). "However, the BCL-6 corepressor (BCOR) enhances the inhibition of BCL-6 in tumour cells." (PMID 34961030, 2021). "BCOR ITDs could also be detected in circulating tumor DNA in CCSK preoperative cases." (PMID 31676003, 2019). "Thus, based on a gene expression array showing induction of BCoR mRNA in primary microvessel endothelial cells in response to tumor-derived stimuli, we conducted an investigation to characterize the expression and function of this transcriptional repressor complex in ECs in more detail." (PMID 27880939, 2017). "BCOR has not previously been demonstrated to control tumour cell proliferation or survival, so how BCOR loss co-operates with MYC to drive oncogenesis remains unclear." (PMID 28262675, 2017). "Factors such as tumor location (supratentorial vs. infratentorial), age at diagnosis, and the presence of molecular markers (e.g., FOXR2, BCOR, CIC, MN1 alterations) are important for differential diagnosis but are not definitive in isolation." (PMID 40647489, 2025). "Neither has been explored in their relationship with biological sex differences; however, FAT4 acts as a tumor-suppressor gene with typically lower expression in tumors, while BCOR (BCL6 corepressor gene) drives oncogenic transformation in neural cells." (PMID 40362575, 2025). "BCOR, a transcriptional corepressor of BCL-6, contributes to tumor progression through its role in polycomb repressive complex 1 (PRC1), underscoring its importance in oncogenesis and potential as a therapeutic target." (PMID 39877469, 2025). "FISH can be performed on 5-μm formalin-fixed, paraffin-embedded tumor sections using probes flanking the YWHAE, BCOR, and ZC3H7B genes." (PMID 39877469, 2025). "In our patient's case, the tumor consisted of small round cells and was CD99+, BCOR+, FLI1+, TLE1−, and NKX2.2−." (PMID 40115314, 2025). "RNA and DNA NGS can allow to detect the BCOR ITD and exclude other molecular traits (including other types of BCOR alterations) which can be observed in other tumor types." (PMID 37658995, 2024).